RNU6-424P (RNA, U6 small nuclear 424, pseudogene)
Gene: Small nuclear RNA gene on chromosome 1 (27,693,731 to 27,693,835, forward strand). Ensembl gene ENSG00000207095.
Homologues: Orthologues: chimpanzee U6 (99% identical), macaque U6 (91% identical). Paralogues in human: RNU6-1083P (89% identical), RNU6-393P (88% identical), RNU6-1024P (87% identical), RNU6-1181P (87% identical), RNU6-11P (87% identical), RNU6-1209P (87% identical), RNU6-1310P (87% identical), RNU6-28P (87% identical), RNU6-37P (87% identical), RNU6-560P (87% identical), RNU6-737P (87% identical), RNU6-797P (87% identical), and 1287 more.